NFATC1 (nuclear factor of activated T cells 1)
Diseases named in the same sentence as NFATC1 in open-access papers (continued):
Sharing a sentence is not in itself a finding about the gene and the disease.
prostate carcinoma (continued). "It is likely that induction of NFATc1 expression that occurred during priming of osteoclast precursors with RANKL was necessary for acquisition of their sensitivity to prostate cancer factors." (PMID 24370273, 2013). "To further confirm that the effect of prostate cancer CM on osteoclastogenesis is mediated by NFATc1 nuclear translocation, we pretreated RANKL-primed bone marrow precursors for 1 h with vehicle (DMSO) or NFAT inhibitor, VIVIT." (PMID 24370273, 2013). "To characterize the signaling pathways induced in osteoclast precursors by prostate cancer cells, we first examined calcium/NFATc1 signaling." (PMID 24370273, 2013). "To determine whether phosphorylation affects transcriptional activity of NFATC1, we transiently overexpressed WT and mutant NFATC1 proteins in three different prostate cancer cell lines, PC-3, DU-145 and LNCaP cells." (PMID 31730483, 2019). "Maybe most interestingly in regard to our data on promotion of prostate cancer cell motility by PIM1 and NFATC1, there were several genes encoding regulators of the cytoskeletal actin network (INF2, FHOD1, ACTN3, CORO1B) and cell adhesion (COL6A2, PXN, ITGA5)." (PMID 31730483, 2019). "As also NFATC1 promotes motility of prostate cancer cells and as PIM-selective inhibitors can block this, we now wanted to investigate whether or not PIM-dependent phosphorylation of NFATC1 is important for migration and invasion of prostate cancer cells." (PMID 31730483, 2019). "In addition to the calcium/NFATc1 signaling pathways, we have demonstrated that soluble factors produced by prostate cancer cells also promoted ERK1/2 activation." (PMID 24370273, 2013). "Thus, prostate cancer factors were found to induce calcium signaling supporting NFATc1 activation in RANKL-primed osteoclast precursors." (PMID 24370273, 2013). "Prostate cancer CM-induced NFATc1 nuclear translocation was attenuated by VIVIT." (PMID 24370273, 2013). "MiR-378a-3p from prostate-cancer-cell-derived EVs promoted osteolysis through activation of the Dyrk1a/Nfatc1/Angptl2 axis in bone marrow macrophages, which played an important role in prostate cancer bone metastasis and could be a potential predictor of metastatic prostate cancer." (PMID 37046819, 2023). "Most interestingly, the positive correlation between NFATC1 and ITGA5 increased along the Gleason score, with the strongest correlation in prostate cancer patients with Gleason ≥8." (PMID 31730483, 2019). "Our data prompted us to examine clinical prostate cancer samples for their expression levels of PIM1, NFATC1 and/or ITGA5 mRNAs." (PMID 31730483, 2019). "While no clear PIM-dependent changes in integrin activity or expression have previously been reported, we now found correlations between PIM1 or NFATC1 mRNA expression levels with ITGA5, both in PC-3 cells and in prostate cancer patient-derived samples." (PMID 31730483, 2019). "In contrast, nuclear localization of NFATc1 was highly sensitive to the presence of RANKL, and was effectively maintained by prostate cancer factors." (PMID 24370273, 2013). "Inhibition of calcium signaling, NFATc1 activation, and ERK1/2 phosphorylation significantly reduced the ability of prostate cancer mediators to stimulate osteoclastogenesis." (PMID 24370273, 2013). "We investigated the effect of prostate cancer CM on NFATc1 protein expression levels and cellular localization in RANKL-primed precursors exposed to prostate cancer CM for 2 h." (PMID 24370273, 2013). "While priming with RANKL resulted in significant increase in NFATc1 protein levels, no additional effect of prostate cancer CM was observed." (PMID 24370273, 2013). "Thus, prostate cancer-derived factors can substitute for RANKL in maintaining calcium signaling and NFATc1 activity." (PMID 24370273, 2013). "We have found that in RANKL-primed precursors NFATc1 protein levels were significantly increased compared to naïve precursors, and were not affected by exposure to prostate cancer CM." (PMID 24370273, 2013).
prostate carcinoma (continued). "Exposure of RANKL-primed precursors to 10% prostate cancer CM resulted in significant increase in the percentage of precursors (69-97% for PC3, 80-93% for LNCaP) exhibiting nuclear NFATc1 compared to negative control." (PMID 24370273, 2013).
rheumatoid arthritis (12 papers, 2017 to 2026). A chronic, systemic autoimmune disorder characterized by inflammation in the synovial membranes and articular surfaces. "The authors demonstrated that RvE1 inhibited osteoclastogenesis and bone resorption, reducing the number of TRAP-positive cells, by suppressing RANKL-induced NFATc1 and c-fos expression in osteoclasts suggesting a possible therapeutic approach with RvE1 to treat rheumatoid arthritis." (PMID 31780864, 2019). "Notably, CSA is a robust inhibitor of CXCL10-induced NFATc1 activation, a mechanism by which CXCL10 regulates the recruitment of inflammatory cells in rheumatoid arthritis." (PMID 35536669, 2022).
leukemia (11 papers, 2016 to 2025). A malignant (clonal) hematologic disorder, involving hematopoietic stem cells and characterized by the presence of primitive or atypical myeloid or lymphoid cells in the bone marrow and the blood. "A deletion on chromosome 12q21.33 (260 kb) was found in the region encoding the ALL-associated gene BTG1, whereas three deletions were found on chromosome 18, one at q21.1 and two at q23, including the 132-kb deletion affecting exon 10 of the leukemia-associated gene NFATC1." (PMID 38777370, 2024). "Two important calcium-regulated genes, calcium/calmodulin-dependent protein kinase II (CAMKII) and a nuclear factor of activated T-cells 1 (NFATc1), are expressed in leukemia cells that are characterized by high levels of ROS." (PMID 30262727, 2018). "Here, we asked, whether increased NFATC1 expression causes resistance to quizartinib, a more potent FLT3ITD inhibitor, or to standard chemotherapy in primary F and FCN leukemia cells in vitro and in vivo." (PMID 31286998, 2019). "Any alteration, such as above or below threshold levels of NFATc1 activity will push the delicate balance towards an unwanted extreme, either resulting in T-cell lymphopenia or, likely in combination with other oncogenic events, leading towards the development of leukaemia." (PMID 27312418, 2016).
lymphoma (11 papers, 2012 to 2025). A malignant (clonal) proliferation of B- lymphocytes or T- lymphocytes which involves the lymph nodes, bone marrow and/or extranodal sites. "We also examined the association between nuclear localization of NFATc1 and CagA in lymphoma cells and HPE responsiveness (complete remission [CR] of lymphoma after HPE) in patients with gastric MALT lymphoma who received first-line HPE." (PMID 39558403, 2024). "These important biological functions of NFATc1 in limiting tumor progression in lymphoma B cells are in line with our current immunohistochemical findings showing a significant association between the nuclear localization of NFATc1, CagA, and HPE responsiveness in gastric MALT lymphoma." (PMID 39558403, 2024). "The immunohistological evaluation of NFATc1 in nearly 300 cases of lymphoma indicates that the majority of tumor lymphocytes express NFATc1 as a cytosolic component despite its absence in classical Hodgkin’s disease and plasma cell proliferations." (PMID 40076009, 2025). "HP infection induces cell cycle arrest of lymphoma cells via activation of CagA-related and NFATc1-dependent signals." (PMID 39558403, 2024). "In contrast, the nuclear localization of NFATc1 was maintained in lymphoma B cells 24 h after HP infection, whereas it decreased 3 h after HP infection in AGS cells." (PMID 39558403, 2024). "Our current study showed that the nuclear localization of NFATc1 in lymphoma cells significantly correlated with the presence of CagA in lymphoma cells and HPE responsiveness in patients with gastric MALT lymphoma." (PMID 39558403, 2024). "This biological significance was further confirmed in tumor samples from patients with gastric MALT lymphoma, in which the nuclear localization of NFATc1 significantly correlated with CagA expression in lymphoma cells and the CR of these tumors." (PMID 39558403, 2024). "Nuclear localization of NFATc1 was significantly downregulated in the lymphoma cells of two patients (cases #1 and #2) who achieved partial remission and CR at 4.00 and 7.00 months, respectively, after the completion of HPE." (PMID 39558403, 2024). "We also assessed serial changes in the nuclear localization of NFATc1 in lymphoma cells before and after HPE completion in four patients with HPE-responsive gastric MALT lymphoma." (PMID 39558403, 2024). "Nuclear localization of CagA was observed in lymphoma cells of the gastric mucosa, and nuclear localization of NFATc1 was observed in the same regions of lymphoma cells expressing CagA." (PMID 39558403, 2024). "Our initial incentive to investigate the role of NFATc1 in BL came from the observation that anti-apoptotic NFATc1/α proteins are expressed in a wide panel of lymphomas." (PMID 37546418, 2023). "The HP-co-cultured lymphoma cells exhibited a G1 phase suppression through the activation of NFATc1 and p21." (PMID 30999581, 2019). "Our results suggest that PD-1/CTLA-4 blockade increases the ability of T cells to infiltrate EBV-induced lymphomas, and to become highly activated (as measured by NFATC1 nuclear translocation)." (PMID 27186886, 2016). "In this study, CagA translocated from HP promoted cell proliferation and inhibited cell cycle progression through tyrosine phosphorylation-dependent and NFATc1-regulated signaling, respectively, and contributed to CR of lymphoma if HP was successfully eradicated." (PMID 39558403, 2024). "CagA and NFATc1 colocalized in the lymphoma cells of patients with HPE-responsive gastric MALT lymphoma, and the combined presence of CagA and nuclear localization of NFATc1 increased the PPV (90.5%) and specificity (87.5%) for HPE responsiveness compared with CagA expression alone." (PMID 39558403, 2024). "Previous studies have revealed nuclear localization of nuclear factor of activated T cell 1 (NFATc1, also known as NFAT2) in lymphoma cells of certain subtypes, including MALT lymphoma, diffuse large B-cell lymphoma (DLBCL), Burkitt’s lymphoma, and Hodgkin’s lymphoma." (PMID 39558403, 2024).
lymphoma (continued). "In this study, we aimed to explore whether HP CagA can induce the nuclear localization of NFATc1 through CagA tyrosine phosphorylation and NFATc1 dephosphorylation in HP co-cultured lymphoma B-cell lines." (PMID 39558403, 2024). "Furthermore, increased NFATC1 expression, as well translocation of NFATC1 to the nucleus, was observed in the smaller lymphomas in PD-1/CTLA-4 treated animals." (PMID 27186886, 2016). "Thus infiltration of T cells into lymphomas and NFATC1 nuclear translocation strongly correlates with reduced lymphoma size in this EBV-infected cord blood model." (PMID 27186886, 2016). "The EBV-induced lymphomas in untreated animals had little if any nuclear NFATC1." (PMID 27186886, 2016). "This suggests that NFATc1 might also be involved in further human lymphomas in which c-Myc is over-expressed, such as in Burkitt ́s lymphomas." (PMID 22764736, 2012). "However, if dysregulated, NFATc1/αA appears to contribute to lymphoma genesis and – as we assume – to further disorders of the lymphoid system." (PMID 22764736, 2012). "Furthermore, we explored whether the nuclear localization of CagA simultaneously activated the nuclear localization of NFATc1 in HP co-cultured lymphoma B cells through the activation of p21." (PMID 39558403, 2024). "Our results highlight RELA, ETS1, NFATC1, and ITGB2 as central players in the pathogenesis of various diseases, including RA, lymphoma, asthma, acute myelocytic leukemia, and leukemogenesis." (PMID 40839671, 2025). "The biological significance of nuclear localization of NFATc1 is accompanied by the activation of CDK inhibitors (p21 and p27), which contribute to G1 arrest in lymphoma B cells." (PMID 39558403, 2024). "Compared with CagA expression or nuclear localization of NFATc1 alone, the combination of CagA expression and nuclear NFATc1 localization showed increased PPV (92.7%) and specificity (86.4%) for HPE responsiveness in these lymphomas." (PMID 39558403, 2024). "Activation of NFATC1 has been demonstrated in tumor tissues of patients with diffuse large B‐cell lymphoma (DLBCL) and cell lines originating from lymphoma." (PMID 34309232, 2021). "Our preliminary results showed that in HP-co-cultured lymphoma cells, CagA upregulated the expressions of p-SHP-2, p-ERK, and Bcl-xL, and nuclear NFATc1 translocation." (PMID 30999581, 2019). "We detected no nuclear localization of NFATc1 in gastric biopsies or remitting lymphoma cells from two other patients (cases #3 and #4) who achieved CR 1.00 and 4.00 months after completing HPE." (PMID 39558403, 2024). "Although we did not determine whether VacA could inhibit the activation of NFATc1 by CagA in lymphoma B cells, our findings showed that CagA, but not VacA, was stimulated by HP in HP-co-cultured B lymphoma cells." (PMID 39558403, 2024). "Of note, although larger lymphomas were much less common in the PD-1/CTLA-4 treated versus untreated animals, when they did occur in the treated animals they had much reduced T cell infiltration and NFATC1 nuclear accumulation in comparison to the smaller tumors." (PMID 27186886, 2016).
atherosclerosis (10 papers, 2013 to 2025). A disease characterized by the build-up of fatty material and calcium deposition in the arterial wall resulting in partial or complete occlusion of the arterial lumen. "Overexpression of NFATc1 and NFATc2 causes Egr-3 upregulation and the excessive activation of endothelial cells, which might lead to vascular disease, such as pathological angiogenesis, inflammation, and atherosclerosis." (PMID 33791348, 2021). "Moreover, a study showed that LRP1-dependent BMPER signaling is required for LPS-induced nuclear factor of activated T cells 1 (NFATc1) activation to induce acute inflammatory responses in endothelial cells, which may cause the initiation of atherosclerosis." (PMID 34124208, 2021). "Intraplaque angiogenesis plays an extremely important role in the pathophysiological mechanisms of atherosclerosis, and NFATc1 promotes neointima formation and atherosclerosis." (PMID 33791348, 2021). "Recent studies demonstrated that NFATc1 plays an important role during the development of atherosclerosis." (PMID 26600673, 2015). "Our previous studies also proved this finding, and we found one of downstream target genes of CD137 was nuclear factor NFATc1, which can regulate the release of inflammation and amplify the inflammatory response in atherosclerosis." (PMID 26600673, 2015). "From above results, OX40-OX40L and/or its downstream signaling intermediates such as NFATc1 will likely prove to be excellent future therapeutic targets for atherosclerosis." (PMID 23593329, 2013). "Recent studies show that NFATc1 may promote inflammation in the progression and regression of atherosclerosis." (PMID 26600673, 2015). "Therefore, the study of NFAT especially the specific mechanism by which NFATc1 induces atherosclerosis development, is very important for a better elaboration the mechanism of by which CD137 and OX40-related signals promote AS progression and the mechanism of atherosclerosis caused by diabetes." (PMID 33791348, 2021). "IL-33 has also been identified as another target of NFATc1 that mediates endothelial dysfunction and vascular wall remodeling, providing a new direction for the study of NFAT-related targeted therapy for atherosclerosis." (PMID 33791348, 2021). "Activated CD137 signaling regulates the expression of NFATc1 and its downstream factors in vascular smooth muscle cells through TRAF6/NF-kB p65 pathways, providing a new target for atherosclerosis therapy." (PMID 33791348, 2021). "Activated CD137 signaling also regulates the expression of NFATc1 and its downstream factors in vascular smooth muscle cells through TRAF6/NF-κB p65 pathways, providing a new target for atherosclerosis treatment." (PMID 33791348, 2021). "NFATc1 is one of the downstream signaling intermediates, and OX40-OX40L may be a good target for future atherosclerosis therapy." (PMID 33791348, 2021).